GPR87 (G protein-coupled receptor 87)
Diseases named in the same sentence as GPR87 in open-access papers (continued):
Sharing a sentence is not in itself a finding about the gene and the disease.
lung adenocarcinoma (5 papers, 2016 to 2025). A carcinoma that arises from the lung and is characterized by the presence of malignant glandular epithelial cells. "The purpose of this study is to examine the association between G protein-coupled receptor 87 (GPR87) and lung adenocarcinoma (LUAD) metastasis and immune infiltration." (PMID 35790819, 2022). "We found that GPR87 was upregulated in lung adenocarcinoma tissues and was significantly associated with poor prognosis of patients with lung adenocarcinoma." (PMID 35008182, 2021). "In this study, we found that GPR87 expression is upregulated in lung adenocarcinoma and is associated with poor patient prognosis." (PMID 35008182, 2021). "Using the Kaplan-Meier survival analysis, we examined the association between GPR87 expression and survival outcomes of patients with lung adenocarcinoma." (PMID 35008182, 2021). "GPR87 is reported as a central player in lung adenocarcinoma and in resistance to immunotherapy, by promoting tumor cell invasion and mediating the immunogenomic landscape." (PMID 35790819, 2022). "To evaluate the functional role of GPR87 overexpression in lung adenocarcinoma progression, we performed invasion and proliferation assays in GPR87-overexpressing lung adenocarcinoma cell lines." (PMID 35008182, 2021). "The public lung adenocarcinoma dataset was used to determine the clinical relevance of GPR87 expression in patients with lung adenocarcinoma." (PMID 35008182, 2021). "After confirming the downregulation of GPR87 in GPR87-silenced cells, we examined the effect of GPR87 silencing on downstream signaling in A549 lung adenocarcinoma cells." (PMID 35008182, 2021). "Our data imply that GPR87 promotes malignant characteristics by activating AKT-eNOS signaling in lung adenocarcinoma cells." (PMID 35008182, 2021). "In this study, the association between GPR87 expression and EMT-related genes was demonstrated for the first time in lung adenocarcinoma." (PMID 35008182, 2021). "Taken together, these results indicate that GPR87 promotes malignant properties by activating AKT-eNOS signaling in lung adenocarcinoma cells." (PMID 35008182, 2021). "Here, we discovered that GPR87 is upregulated in lung adenocarcinoma and overexpressed GPR87 contributes to poor prognosis in patients with lung adenocarcinoma." (PMID 35008182, 2021). "Herein, we demonstrate that GPR87 is upregulated in lung adenocarcinoma and that overexpressed GPR87 contributes to a poor prognosis in lung adenocarcinoma patients." (PMID 35008182, 2021). "In the present study, we elucidated the functional role and molecular mechanism of GPR87 in lung adenocarcinoma." (PMID 35008182, 2021). "When GPR87-silenced lung adenocarcinoma cells were intravenously injected into the tail veins of nude mice, our results indicated that GPR87 depletion suppressed the metastasis of lung adenocarcinoma cells." (PMID 35008182, 2021). "The functional experiments in vitro and in vivo were performed to evaluate the role of GPR87 expression on lung adenocarcinoma metastasis." (PMID 35008182, 2021). "Well- defined preclinical models are needed to better elucidate the biological function of GPR87 in metastasis of lung adenocarcinoma." (PMID 35008182, 2021). "We also found that L-NAME treatment markedly abolished the effects of GPR87 overexpression, indicating that the inhibition of eNOS can inhibit GPR87-induced metastatic properties in lung adenocarcinoma." (PMID 35008182, 2021). "In the present study, we identified that GPR87 is an important effector in promoting malignancy in lung adenocarcinoma." (PMID 35008182, 2021). "Our study revealed that GPR87 has oncogenic functions in lung adenocarcinoma and elucidated the novel regulatory mechanisms that promote lung adenocarcinoma progression." (PMID 35008182, 2021). "Our results are consistent with these findings and support the tumor-promoting effect of GPR87 in lung adenocarcinoma." (PMID 35008182, 2021).
lung adenocarcinoma (continued). "Consistently, L-NAME treatment significantly inhibited A549 lung adenocarcinoma cell invasion by GPR87 overexpression." (PMID 35008182, 2021). "Based on these results, we inferred that GPR87 overexpression promotes lung adenocarcinoma cell invasiveness and plays a critical oncogenic role in lung adenocarcinoma progression." (PMID 35008182, 2021). "This study supports our results, highlighting the oncogenic function of GPR87 in lung adenocarcinoma." (PMID 35008182, 2021). "Our results are consistent with these findings and we have demonstrated that eNOS is a key mediator for GPR87 in the regulation of metastatic properties through the AKT-eNOS-NO signaling pathway in lung adenocarcinoma." (PMID 35008182, 2021). "Collectively, our results indicate that eNOS is a key mediator for GPR87 in the regulation of metastatic properties through the AKT-NO signaling pathway in lung adenocarcinoma." (PMID 35008182, 2021). "In the present study, our findings provide evidence that GPR87 overexpression significantly promotes invasive ability in lung adenocarcinoma cells." (PMID 35008182, 2021). "To investigate the clinical relevance of GPR87 expression in lung adenocarcinoma patients, we analyzed public microarray lung adenocarcinoma datasets from the NCBI Gene Expression Omnibus (GEO) database." (PMID 35008182, 2021). "We therefore, investigated the downstream signaling pathway through which GPR87 promotes lung adenocarcinoma progression by performing a human phospho-kinase screening." (PMID 35008182, 2021). "GPR87-silenced A549-FLuc lung adenocarcinoma cells were intravenously injected into the tail veins of nude mice, and the luminescence signal was visualized once a week." (PMID 35008182, 2021). "Intracellular NO production was induced by LPA treatment and GPR87 overexpression in A549 lung adenocarcinoma cells." (PMID 35008182, 2021). "GPR87 is an orphan G-protein-coupled receptor (GPCR) that represents a potential molecular target for developing novel drugs aimed at treating squamous cell carcinomas (SCCs) or adenocarcinomas of the lungs and bladder." (PMID 40207812, 2025). "Therefore, although we did not perform the experiments in this study, we expect that the combination of a GPR87 inhibitor with an eNOS inhibitor can serve as an attractive therapeutic strategy to achieve clinical benefits in lung adenocarcinoma." (PMID 35008182, 2021). "To further determine whether downregulation of GPR87 inhibited cell proliferation and invasion in lung adenocarcinoma, we performed invasion and proliferation assays in GPR87-silenced lung adenocarcinoma cells." (PMID 35008182, 2021). "Since EMT contributes to the poor prognosis of cancer patients, we examined whether the expression of GPR87 affects EMT in lung adenocarcinoma cells." (PMID 35008182, 2021). "Our results elucidate the mechanism for the oncogenic function of GPR87 in the progression and metastasis of lung adenocarcinoma, and suggest strategies that may improve therapeutic outcomes." (PMID 35008182, 2021). "Finally, we found that eNOS is an important mediator in the downstream mechanisms regulated by GPR87 in lung adenocarcinoma and, indeed, eNOS plays an oncogenic functional role in cancer cells." (PMID 35008182, 2021). "Additionally, we showed that GPR87 overexpression promotes invasiveness and metastasis of lung adenocarcinoma cells." (PMID 35008182, 2021). "Furthermore, we demonstrated that AKT-eNOS-NO signaling is a novel downstream pathway of GPR87 in lung adenocarcinoma." (PMID 35008182, 2021). "Based on our results, we speculate that GPR87 enhances NO production by stimulating eNOS activation, thereby promoting the progression of lung adenocarcinoma." (PMID 35008182, 2021). "In the present study, we elucidated the mechanism of the GPR87-AKT-eNOS-NO pathway for the first time in lung adenocarcinoma; however, further studies are needed to determine whether the GPR87 pathway is the same in other types of cancer." (PMID 35008182, 2021).
lung adenocarcinoma (continued). "However, since the functional role of GPR87 expression has not been established in lung adenocarcinoma, the regulatory mechanisms of GPR87 in lung adenocarcinoma development and progression remain to be elucidated." (PMID 35008182, 2021). "We used GPR87-overexpressing and GPR87-silenced lung adonocarcinoma cell lines, along with in vivo studies, to demonstrate that overexpression of GPR87 promoted invasiveness and metastasis of lung adenocarcinoma cells." (PMID 35008182, 2021). "Furthermore, we show that upregulation of GPR87 in lung adenocarcinoma promoted metastatic properties both in vitro and in vivo through the activation of the AKT-eNOS-NO signaling pathway." (PMID 35008182, 2021). "Furthermore, to investigate the clinical relevance of GPR87 in lung adenocarcinoma, we analyzed public microarray datasets." (PMID 35008182, 2021). "Next, we determined whether LPA treatment and GPR87 overexpression had an effect on NO production in A549 lung adenocarcinoma cells." (PMID 35008182, 2021). "Furthermore, to confirm whether GPR87 promotes metastatic abilities through eNOS activation in A549 lung adenocarcinoma cells, L-NAME, an inhibitor of eNOS, was used." (PMID 35008182, 2021). "GPR87 is upregulated in various cancer; however, the biological function of GPR87 has not yet been established in lung adenocarcinoma." (PMID 35008182, 2021). "However, the biological mechanism of GPR87 in lung adenocarcinoma has not been clearly elucidated." (PMID 35008182, 2021). "However, GPR87 overexpression did not affect the proliferation of lung adenocarcinoma cells." (PMID 35008182, 2021).
melanoma (3 papers, 2020 to 2025). A malignant, usually aggressive tumor composed of atypical, neoplastic melanocytes. "Results from the immunohistochemistry assay revealed that SEMA4D and IFITM1 were down-regulated, while KIF20A and GPR87 were over-expressed in melanoma tissue." (PMID 34659201, 2021). "After transfection with KIF20A-siRNA or GPR87-siRNA, levels of lactate, ATP and glucose uptake as well as extracellular acidification rates were all significantly reduced in these melanoma cells." (PMID 34659201, 2021). "When analyzing the potential biological functions of these proteins in melanoma, we found that silencing SEMA4D or IFITM1 promoted, while silencing KIF20A or GPR87 inhibited the proliferation of melanoma cells in vitro." (PMID 34659201, 2021). "In this study, we present the first evidence that SEMA4D, IFITM1, KIF20A and GPR87 may possess a prognostic value for melanoma." (PMID 34659201, 2021). "Moreover, our findings provide the first indication that KIF20A and GPR87 can regulate the glycolytic ability of melanoma cells." (PMID 34659201, 2021). "In specific, the results of our in vitro experiments suggest that SEMA4D and IFITM1 may function as tumor suppressor genes while KIF20A and GPR87 may function as oncogenes in melanoma." (PMID 34659201, 2021). "Based on these results, it seems likely KIF20A and GPR87 may function as oncogenes through their capacity to regulate glycolysis within melanoma cells." (PMID 34659201, 2021). "Finally, eight genes (GPR87, KIT, SH3GL3, PVRL1, ATP1B1, CDAN1, FAU, and TNFSF14) were identified to be closely associated with the OS in melanoma." (PMID 32411243, 2020). "Our signature consists of diverse genes comprising protective (ATP1B1, CDAN1, FAU, and TNFSF14)) and risky (GPR87, KIT, SH3GL3, and PVRL1), which could be considered gene-related protective and risk patterns in melanoma." (PMID 32411243, 2020). "In our study, we identified two gene expression patterns and generated an 8-gene-based (GPR87, KIT, SH3GL3, PVRL1, ATP1B1, CDAN1, FAU, and TNFSF14) gene signature that could recognize melanoma patients with a high risk of unfavorable clinical outcomes." (PMID 32411243, 2020). "Finally, SEMA4D and IFITM1 may function as tumor suppressor genes, while KIF20A and GPR87 may function as oncogenes in melanoma as revealed from results of in vitro experiments." (PMID 34659201, 2021). "As KIF20A and GPR87 are glycolysis-related genes with poor prognostic potential for patients with melanoma, we next examined the effects of KIF20A and GPR87 on glycolytic ability within melanoma cells." (PMID 34659201, 2021). "All eligible gene sets were analyzed, and the 8 genes (GPR87, KIT, SH3GL3, PVRL1, ATP1B1, CDAN1, FAU, and TNFSF14) with the greatest prognostic impact on melanoma." (PMID 32411243, 2020). "We identified an 8-gene signature (i.e., GPR87, KIT, SH3GL3, PVRL1, ATP1B1, CDAN1, FAU, and TNFSF14) with independent prognostic value on melanoma." (PMID 32411243, 2020).
non-small cell lung carcinoma (3 papers, 2017 to 2022). A group of at least three distinct histological types of lung cancer, including non-small cell squamous cell carcinoma, adenocarcinoma, and large cell carcinoma. "Our study suggests that the expression level of GPR87 can be a predictor of immune cell infiltration and immunotherapy in non-small cell lung cancer." (PMID 35790819, 2022). "The CD4+/CD8+ ratio was higher in the GPR87 high-expression group than the low GPR87 expression group, suggesting that the high-expression group patients were correspondingly poorer for non-small cell lung cancer immunotherapy, consistent with the results of the TIDE algorithm analysis." (PMID 35790819, 2022). "NII and colleagues reported that overexpression of GPR87 in non-small cell lung carcinoma (NSCLC) is significantly correlated with poorer differentiation and that higher expression of GPR87 is significantly associated with poorer survival for patients with NSCLC." (PMID 28288630, 2017).
head and neck cancer (2 papers, 2018 to 2022). A primary or metastatic malignant neoplasm affecting the head and neck. "GPR87 was over-expressed in diverse cancers including lung, cervix, skin, urinary bladder, testis, and head and neck cancers." (PMID 29422775, 2018). "The head and neck cancer data set has only one commonly co-occurring pair {GPR87, CXADR}, partly because the CTS sizes are much smaller, ranging from 2 to 5, and the optimal solutions of sizes larger than 2 vary substantially in the choices of the other gene(s)." (PMID 35338126, 2022).
liver cancer (2 papers, 2021). An epithelial or non-epithelial malignant neoplasm that arises from the liver. "G protein-coupled receptor 87 (GPR87) is a member of the GPCR family and has also been shown to be overexpressed in many tumor tissues, including breast, bladder, pancreatic, and liver cancer." (PMID 35008182, 2021). "Furthermore, GPR87 overexpression promotes cancer cell growth and metastasis by upregulating CD133-positive cancer stem-like cells in liver cancer." (PMID 35008182, 2021).
squamous cell carcinoma (2 papers, 2015 to 2025). A carcinoma arising from squamous epithelial cells. "Neoplastic cells in human Squamous Cell Carcinomas (SCCs) express human GPR87 (hGPR87) in various tissues, including the lung, cervical region, head and neck (larynx, pharynx, tonsils, and tongue), urinary bladder, and placenta." (PMID 40207812, 2025). "While complete biochemical and structural data for GPR87 remain to be experimentally validated, this model serves as a valuable reference for designing inhibitors targeting squamous cell carcinomas." (PMID 40207812, 2025). "First, GPR87 is the only GPCR found to be overexpressed and associated with mutation levels in Squamous Cell Carcinomas (SCCs) of the lung." (PMID 40207812, 2025). "Up-regulation of GPR87 was reported in squamous cell carcinomas (SCC) of the lung, cervix, skin, urinary bladder, testis, and head and neck." (PMID 26473854, 2015).
transitional cell carcinoma of the bladder (2 papers, 2013 to 2020). "This study aimed to clarify the role of GPR87 in urothelial carcinoma of the bladder." (PMID 23752273, 2013).
asthma (1 paper, 2017). "The G protein receptor encoded by GPR87 is a receptor for lysophosphatidic acid (LPA), and LPA may contribute to asthma by regulation of cytokine synthesis and chemotaxis in lymphocytes, contractility and proliferation of smooth muscle cells, and inflammatory signaling in airway epithelium." (PMID 29028809, 2017).
chronic kidney disease (1 paper, 2025). Impairment of the renal function secondary to chronic kidney damage persisting for three or more months. "Recent studies have shown that GPR87 is upregulated in the kidneys of individuals with Chronic Kidney Disease (CKD), suggesting its significant role in renal fibrosis through the promotion of glycolysis and mitochondrial damage." (PMID 40207812, 2025).
esophageal squamous cell carcinoma (1 paper, 2017). Esophageal squamous cell carcinoma (ESCC) is a type of esophageal carcinoma (EC) that can affect any part of the esophagus, but is usually located in the upper or middle third. "Furthermore, overexpression of GPR87 could also increase the proliferating rate of the esophageal squamous cell carcinoma (ESCC) cells, while silencing GPR87 produced the opposite effects, providing further evidence that GPR87 function as an onco-protein." (PMID 28288630, 2017).
gallstones (1 paper, 2020). Solid crystalline precipitates in the biliary tract, usually formed in the gallbladder, resulting in the condition of cholelithiasis. "ALPP and GPR87 exhibited to have a potential for predicting risk of GBC for patients with gallstones." (PMID 32547950, 2020). "ALPP and GPR87 are potential biomarkers for predicting cancer risk in patients with gallstones." (PMID 32547950, 2020).
lymph node metastasis (1 paper, 2022). "High GPR87 levels in LUAD were also associated with a high grade of lymph node metastasis." (PMID 35790819, 2022).
pancreatic ductal adenocarcinoma (1 paper, 2022). An infiltrating adenocarcinoma that arises from the epithelial cells of the pancreas. "During the expansion of pancreatic ductal adenocarcinoma stem cells, the promoter of G protein-coupled receptor 87 (GPR87) is directly bounded by STAT3 to increase its expression." (PMID 35651786, 2022). "On the contrary, GPR87 activates JAK2/STAT3 to form a positive feedback loop to promote the stemness of pancreatic ductal adenocarcinoma cells." (PMID 35651786, 2022).